IL1B (interleukin 1 beta)
Diseases named in the same sentence as IL1B in open-access papers (continued):
Sharing a sentence is not in itself a finding about the gene and the disease.
Hyperglycemia (continued). "Indeed, hyperglycaemia-induced IL-1β expression in retinal endothelial cells is believed to underlie diabetic retinopathy." (PMID 25950006, 2015). "Furthermore, the capability of the current model is limited to the low to medium hyperglycaemia/IL-1β region (see later discussion)." (PMID 25167060, 2014). "It has recently been suggested that NOD-like receptors can be induced by hyperglycemia and oxidative stress products, which could link metabolism and inflammation, particularly through the participation of IL1B." (PMID 24885568, 2014). "Interestingly, hyperglycemia alone increased the expression of IL-6 (P < 0.05) and decreased the expression of IL-1β (P < 0.05), when compared to normal glycemia under inflammatory conditions." (PMID 24000330, 2013). "Finally, Ccl2, Tnfα and Il-1β overexpression reflects the pro-inflammatory environment induced by the hyperglycemia." (PMID 24278148, 2013). "We demonstrated that the microvascular morphological changes of pancreas are highly correlated with progressive inflammatory infiltration and proinflammatory cytokine production, including TNF-α, IL-1β, and IL-6, which could lead to β cell decline and hyperglycemia with age." (PMID 40066372, 2025). "Additionally, humoral factors, including pro-inflammatory cytokines, such as tumor necrosis factor-alpha (TNF-α), interleukin-6 (IL-6), and interleukin-1 beta (IL-1β), further exacerbate hyperglycemia by impairing insulin signaling and increasing hepatic glucose output." (PMID 40868089, 2025). "The evidence showed hyperglycemia to be associated with unfavorable treatment outcomes; altered counts and functioning of dendritic cells, monocytes, and CD4+ T cells; and changes in cytokine levels (mainly INF-γ, IL-17, IL-1β, IL-2, IL-6, IL-10, and TNF-α) in patients with DM-TB." (PMID 39981106, 2024). "This process generally begins with renal injury due to hyperglycemia and later production of reactive oxygen species (ROS), which activate the immune system and lead to leukocyte infiltration in the kidney, as well as the secretion of inflammatory cytokines such as IL-1β and IL-17." (PMID 39518925, 2024). "Moreover, according to the WB analysis, the NLRP3, P2X7, IL-18, and IL-1β protein levels in the retinas of mice in the treatment groups demonstrated similar trends, indicating that 3TC reduced the inflammatory activity induced by hyperglycemia." (PMID 35410316, 2022). "Apart from hyperglycemia, other stimuli may promote intra-islet IL-1β expression and accumulation." (PMID 35629988, 2022). "An increase in intra-islet IL-1β concentrations following hyperglycemia may depend on the activation of the NLRP3 inflammasome in pancreatic beta cells and islet-infiltrating immune cells (especially macrophages), resulting in the processing of pro-IL-1β to the biologically active IL-1β." (PMID 35629988, 2022). "Chronic exposure to pro-inflammatory cytokines such as TNF-α, IL-1β and IL-6 activates the signaling proteins that block the activation of the insulin signaling cascade in the target organs of insulin, including skeletal muscle, adipose tissue and liver, leading to hyperglycemia." (PMID 34201653, 2021). "Supplemental 25-OH-D3 repressed IL-1β secretion and respiratory burst of both cells mostly in R-hens, but promoted monocyte phagocytosis, chemotaxis, and bacterial killing activity in Ad-hens in accompany with relieved hyperglycemia, hyperlipidemia, and systemic inflammation." (PMID 34200930, 2021). "Also, longer after-treatment studies may prove interesting to determine the effect of hyperglycemia normalization on the expression of IL-1β." (PMID 32561825, 2020). "Hence, this study was aimed to investigate whether high concentration of glucose (HG), which mimics the hyperglycemia environment, could initiate vascular calcification through NLRP3/IL-1β inflammasome and the underlying mechanism." (PMID 31938471, 2020).
Hyperglycemia (continued). "Even if longer after-treatment studies may prove interesting to determine the effect of hyperglycemia normalization on the expression of IL-1β, the current results contribute to the knowledge of the relationship between inflammation and changes in glucose metabolism in T2D." (PMID 32561825, 2020). "Notably, the secretion of pro-inflammatory cytokines IL-1β, which are normally secreted by M1 macrophages in higher concentrations, had been found in Mφ, M1, and M2 macrophages, indicating that hyperglycemia conditions could directly induce IL-1β expression." (PMID 30060570, 2018). "Similarly, NLRP3 inflammasome activation in pancreatic β-cells is triggered by hyperglycemia, and subsequent IL-1β production contributes to β-cell death, suggesting the NLRP3 inflammasome as a sensor of chronically elevated glucose and a mediator of pancreatic dysfunction." (PMID 23924318, 2013). "Therefore, the transient effects of EX-4 may be against apoptosis via increasing the IL-1β level in normoglycemia and iNOS via an inhibited IL-1β level in hyperglycemia." (PMID 22844396, 2012). "Additionally, hyperglycemia markedly enhanced renal production of proinflammatory cytokine IL-1β." (PMID 21699681, 2011). "Hyperglycemia significantly upregulates NLRP3 and pro-IL-1β expression via the NF-κB pathway, whereas mitochondrial ROS accumulation and K+ efflux trigger inflammasome assembly, activating caspase-1 and promoting IL-1β/IL-18 maturation and release." (PMID 41487503, 2025). "Studies have identified an inflammatory response in hypothalamic neurons mediated by IL-1β and TNF-α, which impairs insulin signaling and exacerbates hyperglycemia, further linking metabolic dysregulation with neuroinflammatory processes." (PMID 40218134, 2025). "Studies have shown that hyperglycemia activated the production of inflammatory cytokines such as TNF, IL6, and IL1B, which contribute to kidney damage." (PMID 39911324, 2025). "Long-term exposure to high-fat diets or hyperglycemia can impair endothelial cell function via inflammatory cytokines such as TNF-α, IL-1β, IL-6, and MCP-1." (PMID 40276785, 2025). "Hyperglycemia and adipose tissue create a low-grade inflammatory state, increasing pro-inflammatory factors (e.g., TNF-α, IL-1β, IL-6) and ECM degradation." (PMID 41158135, 2025). "Further investigation demonstrated that NLRP3 mediates hyperglycemia-induced inflammation, and NLRP3 inhibition attenuated IL-1β activation and the decline in the steroidogenic capacity in the Leydig cells." (PMID 40940788, 2025). "The priming phase, triggered by hyperglycemia, oxidative stress, and lipotoxicity, activates NF-κB signaling, leading to increased NLRP3 expression and the production of pro-IL-1β and pro-IL-18." (PMID 40427455, 2025). "Conversely, 3-MA enhanced the NLRP3 expression and IL-1β maturation, demonstrating autophagy’s essential role in suppressing NLRP3-mediated inflammation under hyperglycemia." (PMID 40940788, 2025). "Hyperglycemia induces the assembly and activation of the NLRP3 inflammasome, prompting the release of numerous inflammatory factors, such as IL-1β and IL-18." (PMID 41394140, 2025). "The CoPP-induced HO-1 also led to downregulations of IL-1β and TNFα, two inflammatory markers known to be expressed in RPE cells under hyperglycemia." (PMID 39857426, 2025). "Our data also indicate that hyperglycemia induces caspase-1 activation initially but IL-1β sustains caspase-1 activation via caspase-1/IL-1β/IL-1R1 feedback and we identified RIP2 as mediator for both hyperglycemia- and IL-1β-induced caspase-1 activation." (PMID 39483336, 2024). "Although our study used Müller cells to demonstrate hyperglycemia-induced caspase-1/IL-1β/IL-1R1 feedback signaling, other retinal cells might be capable of producing similar feedback cycles leading to sustained caspase-1 activation and prolonged IL-1β production." (PMID 39483336, 2024).
Hyperglycemia (continued). "When islet cells are exposed to chronic hyperglycemia, they will trigger the activation of NLRP3 and the release of IL-1β and IL-18." (PMID 39328924, 2024). "Hyperglycemia, hyperlipidemia, and hyperuricemia trigger the NLRP3 inflammasome, linking metabolic stress in DN to pro-inflammatory responses via IL–1β and IL–18." (PMID 38890983, 2024). "Since RIP2 upregulation was crucial for hyperglycemia-driven caspase-1 activation, we further investigated the role of RIP2 in IL-1β-induced caspase-1 activation." (PMID 39483336, 2024). "In patients with hyperglycemia, researchers have detected chronic low-grade, subclinical inflammation mediated by TNF-α, COX-2, IL-1β, IL-6, and MCP-1, which is responsible for vascular complications." (PMID 36982499, 2023). "In turn, the increased glucose metabolism imposed by sustained hyperglycemia seems to enhance SARS-CoV-2’s entry and subsequent replication, as well as exacerbated immune responses such as tumor necrosis factor-α, interleukin (IL)-1β, and IL-625,26." (PMID 38123659, 2023). "Previous studies have shown that this miRNA is one of the lipid metabolism-related miRNAs, and its upregulation correlates with hyperglycemia, hyperlipidemia, and inflammation markers, such as CRP and IL-1β." (PMID 36989330, 2023). "Hyperglycemia, a diabetes-related endogenous DAMP, can provide a priming signal in NLRP3 inflammasome activation, increasing the transcription of the IL-1β gene and, ultimately, the secretion of pro-ILs." (PMID 37238986, 2023). "After confirming hyperglycemia, the mice received an intravitreal injection of either proinflammatory cytokines (TNF-α and IL-1β) or vehicle." (PMID 36895267, 2023). "The expression of NT5DC3 declined significantly during hyperglycemia, while that of other proteins, such as p-PI3K, p-AKT, p-mTOR, IL-1β, and TNF-α, was substantially higher." (PMID 36553697, 2022). "Findings from experimental models of hyperglycemia suggest that TGF-β1, IL-1β, renin, and ALPK1 levels in the kidney or blood is associated with ALPK1-induced fibrotic kidney injury." (PMID 36139553, 2022). "Reduction of the kidney SOD enzymes was demonstrated in KK/Ta-Akita mice after 5-week hyperglycemia mediated by TNF-α and interleukin-1β (IL-1β)." (PMID 34326888, 2021). "Persistent hyperglycemia activates NF-κB, which increases the expression of various adhesion molecules and proinflammatory cytokines (i.e., ICAM-1, MCP-1, IL-1β, and IL-6)." (PMID 34281287, 2021). "Hyperglycemia can trigger NLRP3 overactivation and promote the production of cleaved caspase-1, thus accelerating the maturation and release of IL-1β and IL-18, which induce pyroptosis and finally lead to cardiac dysfunction and heart failure." (PMID 35096293, 2021). "Metabolic insults, including SFAs, pro-inflammatory adipokines, hyperglycemia and endotoxemia, represent major stimuli of NLRP3 inflammasome activation, and subsequent IL-1β production, in adipose tissue." (PMID 32545355, 2020). "A study showed that inflammation due to hyperglycemia leads to the activation of PKCα, which then activates NF-κB by inducing p38 and ERK1/2 to release IL-1β." (PMID 32429534, 2020). "Hyperglycemia reportedly aggravates renal I/R injury by exacerbating the inflammatory response, as indicated by significantly increased TNF-α and IL-1β levels in serum or renal tissues." (PMID 31441362, 2019). "Treatment of Nrf2 activator DMF (HG/DMF) partly restored hyperglycemia-induced IL6 secretion, while it completely restored the secretion of IL1β and MCP1 compared to the HG/VEH group." (PMID 31616304, 2019). "Hyperglycemia is also shown to stimulate the expression of NLRP3, resulting in increased secretion of cytokines IL-1β and IL-18." (PMID 31281401, 2019). "Hyperglycemia and ROS production also promote TLR-2 and TLR-4 activation, with release of TNF-α, IL-1β, IL-8, monocyte chemoattractant protein (MCP-1), vascular cell adhesion molecule 1 (VCAM-1), intracellular adhesion molecule 1 (ICAM-1)." (PMID 31835864, 2019).
Hyperglycemia (continued). "It is known that hyperglycemia increases the production of pro-inflammatory cytokines like TNF-α, IL-1β, and IL-6, which act by way of NF-kB." (PMID 29694627, 2018). "In another study of human macrophages, hyperglycemia enhanced the expression of the M1 cytokines TNF-α and IL-1β as well as M2 cytokine IL-1Ra expression." (PMID 29081777, 2017). "In conclusion, hyperglycemia and hyperlipidemia can lead to the activation of NLRP3 inflammasomes, and their downstream molecules, including caspase-1, IL-1β, and IL-18, in the glomerular mesangium." (PMID 28708885, 2017). "It is widely accepted that hyperglycemia stress, increases cytokines secretion such as TNF-α, IL-6 and IL-1β and alters gene expression profile in targeted cells." (PMID 27942499, 2016). "For instance, hyperglycaemia-induced reactive oxygen species production resulted in activation of PKC and NFκB which, in turn, induced proinflammatory cytokines, TNFα and IL1β." (PMID 25883984, 2015). "Our results show that G. asiatica fruit extract decreases IL-1β and TNF-α induced during hyperglycemia." (PMID 26347423, 2015). "The key markers of oxidative stress and inflammation such as inflammatory cytokines (IL-1β, IL-6, and TNF-α) and immunoregulatory cytokines (IL-4 and IFN-γ) were increased in kidneys along with significant hyperglycemia." (PMID 25295146, 2014). "Relative to the effect of hyperinsulinaemia alone, combined hyperglycaemia and hyperinsulinaemia led to a further increase in IL1A, IL1B and CCL3 mRNA levels." (PMID 18290856, 2008). "Combined hyperglycaemia and hyperinsulinaemia led to enhanced IL1A, interleukin-1 beta (IL1B) and CCL3 mRNA levels upon LPS stimulation." (PMID 18290856, 2008). "In contrast, hyperinsulinaemia enhanced LPS-induced gene expression of several cytokine genes, and its effect on mRNA induction of IL1A, IL1B and CCL3 was especially clear in the concurrent presence of hyperglycaemia." (PMID 18290856, 2008). "Hyperglycemia-driven ROS accumulation promotes the overexpression of pro-inflammatory cytokines (e.g., TNF-α, IL-1β), matrix metalloproteinases (MMPs), and suppression of tissue inhibitors of metalloproteinases (TIMPs), ultimately resulting in extracellular matrix degradation." (PMID 40728954, 2025). "In contrast, in chickens, STZ-induced hyperglycemia led to non-significant upward trends in NF-κB p-p65 and IL-1β concentrations as well as a non-significant downward trend in IL-10." (PMID 41463431, 2025). "Hyperglycemia triggers immune cells to release inflammatory mediators (including TNF-α, IL-1β, IL-6, NF-κB, TGF-β, and adhesion molecules), which further contribute to β-cell dysfunction, insulin resistance, and progression of complications such as vascular damage, neuropathy, and CVD cell loss." (PMID 40299501, 2025). "The present findings showed that hyperglycemia promoted the pro-inflammatory phenotype in macrophages, which was characterized by increased expressions of marker pro-inflammatory mediators, including TNF-α, IL-6, IL-1β, and iNOS." (PMID 40001441, 2025). "Additionally, hyperglycemia-induced mitochondrial ROS overproduction facilitates NLRP3 inflammasome activation, resulting in caspase-1-dependent maturation and the release of IL-1β." (PMID 41321403, 2025). "The levels of IL-1β and IL-2 were not affected by different glucose concentrations, and the differences for these cytokines in hypo-, normo-, and hyperglycemia were not statistically significant." (PMID 38542084, 2024). "In addition, stress-induced hyperglycemia can also trigger an inflammatory response, such as increasing the production of inflammatory cytokines (such as TNF-α, IL-1β, and IL-6), which further exacerbate lung tissue inflammation." (PMID 37658378, 2023). "Pretreatment with insulin or metformin did not modify the decreased secretion of IL-1β observed under hyperglycemia, and resulted in a significantly lesser secretion in comparison with the infected placental explants exposed to 10 mM glucose." (PMID 36982317, 2023).
Hyperglycemia (continued). "This included hyperglycemia, dyslipidemia (elevated TG and reduced HDL), oxidative stress (increased plasma 7α- and 7β-hydroxycholesterol), and heightened inflammation markers (hs-CRP and IL-1β) in the T2DM group." (PMID 37710315, 2023). "Hyperglycemia can also increase the production of reactive oxygen species (ROS), providing the second signal, called the activation signal, as well as initiating NLRP3 complex assembly and active IL-18 and IL-1β production." (PMID 37238986, 2023). "In order to investigate whether lipid signaling might be the missing link between hyperglycemia and mesangial dysfunction in DKD, lipidomic analysis of mesangial cells stimulated with PDGF-BB or IL-1β for 24 h was performed." (PMID 35513427, 2022). "Persistent hyperglycemia in pancreatic islets induces ROS accumulation, leading to elevated thioredoxin-interacting protein (TXNIP), activation of the NLRP3 inflammasome, and induction of caspase-1-dependent IL-1β maturation." (PMID 35844498, 2022). "Interestingly, hyperglycemia has been reported to activate NLRP3 inflammasomes and downstream effector inflammatory cytokines, including TNF-α and IL-1β, which are believed to induce programmed proinflammatory cell death (pyroptosis)." (PMID 35453376, 2022). "Previous studies have demonstrated that hyperglycemia activates the innate immune response mediated by TLR2, TLR4, and the NLRP3 inflammasome, inducing the production of various proinflammatory cytokines, including IL-1β, IL18, IL-6, and TNFα." (PMID 34356130, 2021). "In stroke models using diabetic rats, hyperglycemia increases neutrophil adhesion and transmigration, and also increases expression of TNF, IL-1β, E-selectin, soluble intercellular adhesion molecules (sICAMs), endothelial NO synthase (eNOS) and inducible nitric oxide synthase (iNOS)." (PMID 34054705, 2021). "Hyperglycaemia‐induced oxidative stress promotes inflammation through increased endothelial cell damage, microvascular permeability and increased release of pro‐inflammatory cytokines, including TNF‐α, interlukin‐1β (IL‐1β) and interlukin‐6 (IL‐6)." (PMID 33108705, 2020). "In an excellent agreement, the present data revealed that hyperglycemia could induce the activation of the NLRP3 inflammasome and ultimately lead to the increased expression of IL-1β and IL-18." (PMID 31178664, 2019). "Islets from another two donors not used for RNA-Seq were initially treated with IL-1β and EC for 24 h and subsequently further stressed with hyperglycemia." (PMID 31781116, 2019). "Furthermore, hyperglycaemia-induced oxidative stress can also lead to the production of inflammatory factors such as TNF-α and IL-1β." (PMID 30838453, 2019). "Similarly, our current study verified that persistent hyperglycemia in diabetic rats was followed by increased TNF-α and IL-1β levels within kidney tissues, leading to a state of chronic, low-grade inflammation that intensified after I/R treatment." (PMID 31441362, 2019). "A significant upregulation in IL-1β (p ≤ 0.01) expression was identified with high hyperglycemia (45 mM) independent of a change in TNF-α expression." (PMID 30470798, 2018). "In primary human monocyte-derived macrophages, hyperglycemia induces the production of the prototype M1 cytokines tumor necrosis factor-α (TNF-α), interleukin-1β (IL-1β), and IL-6, but inhibits the M2 cytokines IL-1Ra and C-C motif chemokine ligand 18 (CCL18) during macrophage differentiation." (PMID 29850615, 2018). "Previously, it has been suggested that hyperglycemia-induced ROS production led to renal dysfunction by activating NFκB, a common stress response gene, which, in turn, induced proinflammatory cytokines production including TNF-α and IL1-β." (PMID 23862157, 2013). "In contrast, IL-1β blockade is a selective mechanism that does not promote fluid retention, hypertension, hyperglycemia or any other significant metabolic alterations." (PMID 22438931, 2012).